SPTA1 (spectrin alpha, erythrocytic 1)
Diseases named in the same sentence as SPTA1 in open-access papers (continued):
Sharing a sentence is not in itself a finding about the gene and the disease.
metastatic cancer (1 paper, 2016). A carcinoma which has spread from the original site of growth to another anatomic site. "Adenocarcinoma-associated reductions in spectrins, SPTB and SPTA1, and ankrin (ANK1) all interact with each another to regulate cell shape and membrane integrity, so paralleled changes likely reflect changes in cell adherence, which is a known hallmark of metastatic cancer." (PMID 27799870, 2016).
microcephaly (1 paper, 2016). A congenital or acquired developmental disorder in which the circumference of the head is smaller than normal for the person's age and sex. "SPTA1 is associated with spinocerebellar ataxia which also has microcephaly as one of its physical manifestations." (PMID 29333229, 2016).
neuroblastoma (1 paper, 2022). Neuroblastoma (NB) is the most common solid, extracranial childhood tumor. "However, there were few studies focused on SPTA1 as the potential therapeutic molecular target in neuroblastoma." (PMID 35846139, 2022). "Furthermore, our study indicated that CD8 T cells and SPTA1 might be important in neuroblastoma initiation, while type I interferons played a significant role in neuroblastoma metastasis." (PMID 35846139, 2022).
polycythemia (1 paper, 2023). Abnormally high mass or concentration of red blood cells in the blood, either due to an increase in erythropoiesis or a decrease in plasma volume. "Of note, the deficiency or mutation of the genes such as EPB42, SPTB and SPTA1 can cause hereditary polycythemia, 25], which is also an important cause of hemolytic anemia." (PMID 37507679, 2023).
progeria (1 paper, 2024). "The volcano plot showed a significant number of upregulated proteins in progeria compared with young donors, including serotransferrin (TF), spectrin alpha chain (SPTA1), insulin-like growth factor-binding protein complex acid labile subunit (IGFALS), and others." (PMID 38141925, 2024).
protein deficiency (1 paper, 2023). "Previous research has shown that erythrocyte membrane protein deficiency caused by pathogenic mutations in the ANK1, SLC4A1, SPTA1, SPTB, and EPB42 genes is the molecular pathogenesis of HS." (PMID 36647015, 2023).
somatotropinomas (1 paper, 2025). "Among the genes included in this pathway, recent studies have suggested that FANCD2, SPTA1, TYRO3, and ZNF335 genes are emerging as key players in immune response and regulating tumorigenesis, even if their role has not been studied in TME of somatotropinomas." (PMID 40415137, 2025).
thymic adenocarcinoma (1 paper, 2017).
upper tract urothelial carcinomas (1 paper, 2025). "In bladder and upper tract urothelial carcinomas (UTUC), KMT2C co-occurred with genes such as SPTA1 and LRP1B, suggesting a hypermutated, immunoresponsive phenotype." (PMID 41395625, 2025).
Zika virus infection (1 paper, 2016). "The novel interactions of FNDC3B with IFITM3 and SPTA1, ARPC1B and AGTR2 with IFITM1 may shed light on mechanisms of host invasion underlying cytoskeletal re-arrangements that follow Zika virus infection." (PMID 29333229, 2016).
cancer (18 papers, 2014 to 2025). A tumor composed of atypical neoplastic, often pleomorphic cells that invade other tissues. "Other studies have linked SPTA1 to colorectal and small cell lung cancers." (PMID 39061186, 2024). "Associations with SPTA1, PIK3CA, and MAP3K1 mutations suggest the role of DDIT3 in diverse pathways in cancer progression." (PMID 38911383, 2024). "In contrast, other genes, such as SPTA1, which we found to be associated with HDV, appear significantly mutated in multiple other cancer types." (PMID 32873799, 2020). "The MSigDB Cancer Neighborhood highlighted cancer-associated genes, TAL1, ANK1, SPTB, SPTA1, PRDX2, MAP2K3, etc.." (PMID 25522020, 2014). "PCDHGC5, PCDHAC2, SPTA1, XIRP2 and FLG seemed unrelated with cancer based the reference study." (PMID 27835590, 2016).
tumor (17 papers, 2015 to 2025). "It seemed that ACVR2A, FANCA, RBM10, and SPTA1 mutations might have important functions in tumour development for different subtypes and different molecular characteristics in Chinese patients." (PMID 38024139, 2023). "Tumor-associated reductions in SPTB were associated with similar reductions in SPTA1 (70%), SLC4A1 (60%), and ANK1 (70%) in tumor tissue when compared to control tissue." (PMID 27799870, 2016). "Among the genes that are mutated between 5 to 20% in TCGA GBM tumor samples, we found mutations in NF1, SPTA1, TCHH and ATRX genes, although, the other genes like PIK3R1, PIK3CA, RB1, IDH1 and KEL were not mutated in any cell line." (PMID 26496030, 2015). "SPTA1 may potentially influence the TME by promoting tumor cell invasiveness and modulating the interaction between tumor cells and surrounding stromal cells and consequently enhance tumor dissemination of tumors." (PMID 40415137, 2025).
infection (7 papers, 2016 to 2026). The state of being infected such as from the introduction of a foreign agent such as serum, vaccine, antigenic substance or organism. "After 24 h post-infection with C. jejuni (intracellular survival), the expression of 40 genes was up-regulated in HT-29 treated with EcN, and one of these genes (encoding SPTA1) was uniquely associated with EcN." (PMID 28878749, 2017). "Considering that IFITM1 and IFITM3 regulate permeability of the cell membrane, it is plausible that SPTA1 is also involved in aiding the host cell’s architecture to impede infection." (PMID 29333229, 2016).
neurological disease (2 papers, 2022 to 2026). "In addition, mutations in various members of the spectrin gene family are associated with erythroid cell disorders (SPTA1, SPTB) and neurological disorders (SPTAN1, SPTBN1, SPTBN2, and SPTBN4); however, no human genotype-phenotype correlation has been established for SPTBN5 to date." (PMID 35782384, 2022).
adenocarcinoma (1 paper, 2016). A common cancer characterized by the presence of malignant glandular cells. "Reductions in SPTA1 and SPTB were indirectly associated with APEX1, which showed a 2.7-fold increase in adenocarcinoma compared to non-malignant tissue and was consistently elevated in 82% of subjects." (PMID 27799870, 2016).
SPTA1 also shares sentences with these, for which no sentence is quoted: breast carcinoma (3 papers); glioma (2); melanoma (2); prostate carcinoma (2); Spherocytosis (2); Alpha-thalassemia (1); angiosarcoma (1); cholangiocarcinoma (1); cholelithiasis (1); colorectal adenoma (1); cyst (1); dilated cardiomyopathy (1); elliptocytosis type 2 (1); erythropoietic porphyria (1); erythropoietic protoporphyria (1); glaucoma (1); hematopoietic diseases (1); hydrops fetalis (1); hypogammaglobulinemia (1); ischemia (1); ischemic stroke (1); lung carcinoma (1); lung squamous cell carcinoma (1); mental retardation (1); multiple sclerosis (1); neurodegenerative disease (1); papillary thyroid carcinoma (1); primary progressive multiple sclerosis (1); sickle beta thalassemia (1); small cell lung carcinoma (1).
A further 8 diseases each share a sentence with SPTA1 in 1 paper.